CCDC71L (coiled-coil domain containing 71 like)
Synonyms: C7orf74; FLJ36031
Tractability: PROTAC: ubiquitination databases record sites on it; its protein half-life has been measured.
Gene: Protein-coding gene on chromosome 7 (106,654,360 to 106,661,158, reverse strand). Ensembl gene ENSG00000253276.
Subcellular location (Human Protein Atlas): Actin filaments; Golgi apparatus; Cytosol
Genetic constraint (gnomAD): Loss-of-function variants: 6 observed, 6.22 expected, observed/expected ratio (o/e) 0.96, 90% interval 0.52 to 1.75. That is too few expected variants to judge how well the gene tolerates losing a copy. Missense variants: 366 observed, 290.68 expected, observed/expected ratio (o/e) 1.26, 90% interval 1.15 to 1.37. Synonymous variants: 204 observed, 138.79 expected, observed/expected ratio (o/e) 1.47, 90% interval 1.31 to 1.65.
Homologues: Orthologues: macaque CCDC71L (98% identical), pig CCDC71L (91% identical), dog CCDC71L (85% identical), rat Ccdc71l (74% identical), mouse Ccdc71l (74% identical), chimpanzee CCDC71L (54% identical), tropical clawed frog ccdc71l (42% identical). Paralogues in human: CCDC71 (28% identical).
Diseases named in the same sentence as CCDC71L in open-access papers:
CCDC71L is named in the same sentence as 5 diseases in open-access papers, as found by Europe PMC text mining. Sharing a sentence is not in itself a finding about the gene and the disease. The quoted sentences say what the papers report.
atherosclerosis (1 paper, 2024). A disease characterized by the build-up of fatty material and calcium deposition in the arterial wall resulting in partial or complete occlusion of the arterial lumen. "In genetically predicted levels, higher expression of ANXA5, CCDC71L, MED8, MRAS, MRPS6, NTAN1, and SLA5A3 was positively associated with atherosclerosis risk." (PMID 39766313, 2024).
Stroke (1 paper, 2018). Sudden impairment of blood flow to a part of the brain due to occlusion or rupture of an artery to the brain. "We next assessed if the four genes (CCDC71L, PRKAR2B, ADAMTS9, LOXL4) identified through colocalization of cIMT/carotid plaque with tissue-specific eQTLs also showed evidence for colocalization with CHD and stroke traits." (PMID 30510157, 2018).
triple-negative breast carcinoma (1 paper, 2021). An invasive breast carcinoma which is negative for expression of estrogen receptor (ER), progesterone receptor (PR), and human epidermal growth factor receptor 2 (HER2). "LINC00514 promote cell proliferation, migration and invasion in triple-negative breast cancer by targeting the miR-6504-5p/miR-3139/CCDC71L axis in TNBC." (PMID 33757509, 2021).
cancer (2 papers, 2021 to 2024). A tumor composed of atypical neoplastic, often pleomorphic cells that invade other tissues. "Our present study identified CCDC71L, a novel mRNA that has not been explored in cancers, as the target of miR-6504-5p and miR-3139." (PMID 33757509, 2021). "Since there are almost no reports on the correlation between the CCDC71L gene and cancer in the published literature, we conducted RT-qPCR to detect the expression of 8 other potential downstream genes following STAT5A overexpression in AGS cells or STAT5A interference in SGC-7901 cells." (PMID 38879589, 2024).
tumor (2 papers, 2021 to 2025). "Rescue assay verified that overexpressed CCDC71L countervailed the anti-tumor influence of LINC00514 knockdown on TNBC cell proliferation, migration, invasion and apoptosis." (PMID 33757509, 2021). "Coiled-coil domain-containing 71 like (CCDC71L), a novel prognostic marker and potential immunotherapy target in the lipid metabolism of HNSCC, promotes tumor progression by enhancing the activity of Tregs and facilitating the polarization of M2 macrophages." (PMID 40821122, 2025).